CP (ceruloplasmin)
Diseases named in the same sentence as CP in open-access papers (continued):
Sharing a sentence is not in itself a finding about the gene and the disease.
Parkinson disease (35 papers, 2011 to 2026). A progressive degenerative disorder of the central nervous system characterized by loss of dopamine producing neurons in the substantia nigra and the presence of Lewy bodies in the substantia nigra and locus coeruleus. "In a second report of the same study, the usefulness of the ferroxidase ceruloplasmin (CP) as a biomarker was emphasized, associating the low activity of this enzyme in Parkinson’s disease with iron overload in the substantia nigra." (PMID 36829773, 2023). "Significant sex differences were further found in 61 of 71 circulating cardiovascular disease biomarkers, including ceruloplasmin, which exists in higher levels in women than men and is decreased in association with Parkinson's disease." (PMID 33758788, 2021). "Parkinsonism seen in WD has been associated with the nigrostriatal dopaminergic deficit and reduced ceruloplasmin levels, leading to iron and copper accumulation." (PMID 33354453, 2020). "Recent studies have indicated that a deficiency in CP contributes to Parkinson’s disease through increased activities of iron accumulation and oxidative stress in the substantia nigra." (PMID 31816602, 2019). "Dozens of ceruloplasmin mutations have been identified and some induce Parkinsonism in affected individuals." (PMID 24527451, 2014). "Ceruloplasmin is relevant to neurodegeneration because loss of function ceruloplasmin mutations lead to extrapyramidal symptoms and parkinsonism associated with iron toxicity." (PMID 23536801, 2013). "The present systematic review and meta-analysis aims to establish whether the brain, cerebrospinal fluid (CSF), serum/plasma whole blood, urine, and hair levels of copper, ceruloplasmin, zinc, and manganese are related to the risk for Parkinson's disease (PD)." (PMID 41677652, 2026). "Further evidence of ceruloplasmin malfunction in Parkinson's disease has also been derived from studying the ceruloplasmin gene; five variants of ceruloplasmin were found in a screening study in a cohort of patients who displayed increased substantia nigra echogenicity." (PMID 24672633, 2014). "On the other hand, CP, or ceruloplasmin, is a copper‐binding glycoprotein involved in iron metabolism and defense against oxidative stress; decreased CP activity is associated with advanced age and age‐related diseases, such as Parkinson's and Alzheimer's disease." (PMID 41078088, 2025). "Although numerous previous studies showed that ceruloplasmin deficiency is associated with Alzheimer’s disease, Parkinson’s disease, and other neurodegenerative diseases in patients and rat models, little is known about the therapeutic function of ceruloplasmin in ferroptosis after ICH." (PMID 33281547, 2020). "In Parkinson's disease, the ferroxidase ceruloplasmin (Cp) is oxidized and deaminated by pathological CSF." (PMID 36340696, 2022). "In Parkinson's disease, the ferroxidase ceruloplasmin (Cp) is oxidized and deamidated by the pathological cerebrospinal fluid (CSF) environment." (PMID 32968118, 2020). "One way of addressing this issue involves comparing the ability of moderate iron chelation treatment to reducing both SN iron levels and United Parkinson’s Disease Rating Scale (UPDRS) scores in PD patients according to the level of ceruloplasmin activity." (PMID 25943368, 2015). "Parkinsonism and iron concentration are attenuated by iron chelation with deferiprone in CP−/− mice and aCP." (PMID 26146528, 2015). "Ceruloplasmin, due to its antioxidant properties and its role as an iron regulator in the brain, remains an attractive target for new therapeutic strategies in Parkinson's disease." (PMID 24672633, 2014). "This pilot study explored whether the ceruloplasmin (CP) and ferritin (FT) levels in ocular fluids could serve as biomarkers for early neurodegenerative diseases (Alzheimer’s, Parkinson’s, and other dementias)." (PMID 40650085, 2025).
Parkinson disease (continued). "Nevertheless, decreased serum CP levels have been detected in Parkinson and Alzheimer’s disease cases compared to healthy controls, indicating that this deficiency may contribute to neuronal cell death due to an iron-mediated increase in free radicals." (PMID 35207439, 2022). "As such, copper-induced ceruloplasmin expression could be an experimental strategy against the deleterious effects of iron deposits in Parkinson's disease." (PMID 24672633, 2014). "In addition, copper-dependent ferroxidase activity of ceruloplasmin has been continuously reported to be reduced in samples from Parkinson's disease patients." (PMID 24672633, 2014). "A decreasing ferroxidase activity mediated by ceruloplasmin in the Parkinson’s disease brain could result in a lower capacity for cellular iron export." (PMID 23055972, 2012). "In response to YS administration, we also found an increase in the expression of ceruloplasmin (Cp), a ferroxidase enzyme present in CSF which has a neuroprotective role during cerebral ischemia and displays oxidative deamidation in the CSF of Alzheimer’s and Parkinson’s disease patients." (PMID 37628730, 2023). "Also, ceruloplasmin-knockout mice developed Parkinsonism that was reversed by iron chelation." (PMID 29593525, 2018). "Ceruloplasmin activity is decreased in Parkinson's disease; to our knowledge, there are no studies that show or refute any relationship between ATP7B dysfunction and decreased ceruloplasmin activity in Parkinson's disease." (PMID 24672633, 2014).
ovarian carcinoma (31 papers, 2010 to 2025). A malignant neoplasm originating from the surface ovarian epithelium. "Recent study has shown that LINC00176 promotes ovarian cancer progression by up-regulating the CP expression." (PMID 38385087, 2024). "Inhibiting lncRNA-SAMMSON and lncRNA-ceruloplasmin demonstrated anti-cancer effects in melanoma and ovarian cancer, respectively." (PMID 38226979, 2024). "Polyethylenimine (PEI)-based magnetic iron oxide nanocomplexes were used for drug delivery in genetically matched CIS-resistant (A2780/CP) and -sensitive (A2780) ovarian cancer cells in the presence of a 20 mT static magnetic field." (PMID 37771439, 2023). "For instance, WFA binds to the LacdiNAc structure (GalNAcβ1-3/4GlcNAc) containing the terminal GalNAc of N-glycans on prostate-specific antigens and ceruloplasmin in prostate cancer and ovarian cancer, respectively." (PMID 35563555, 2022). "Elevated serum ceruloplasmin levels have been found in lung cancer, colon carcinoma, epithelial ovarian cancer and bile duct cancer." (PMID 34413268, 2021). "The LINC00176/BCL3/CP axis facilitates the epithelial-mesenchymal transition (EMT) process in ovarian cancer." (PMID 34413268, 2021). "Delivery of si‐LINC00176, oe‐LINC00176, si‐BCL3 and si‐CP plasmids was conducted to explore the effects of LINC00176 on ovarian cancer." (PMID 31668012, 2020). "Hereby, the aim of the study was to uncover the function of lncRNA LINC00176 in the development and progression of ovarian cancer by regulating ceruloplasmin (CP)." (PMID 31668012, 2020). "Our results demonstrate that restored LINC00176 initiates tumorigenesis in ovarian cancer by increasing CP expression via recruiting BCL3, the mechanism of which represented a potential and promising therapeutic target for the disease." (PMID 31668012, 2020). "Ceruloplasmin was also identified in serum from ovarian cancer patients as a possible prognostic biomarker of chemoresistance." (PMID 33059744, 2020). "Cytotoxic activity of the complexes of the four series was studied against two pairs of human ovarian carcinoma cell lines, the cDDP-sensivitive 2008 and A2780, and their resistant counterparts, C13* and A2780/CP." (PMID 31817267, 2019). "To determine the crucial miRNAs involved in ovarian cancer cisplatin resistance, we performed microarray assay to profile the global expression of mature miRNAs in A2780 and A2780/CP cell lines." (PMID 26238185, 2015). "These previous observations support our finding that the concentration of ceruloplasmin was significantly lower in the ascites fluids of chemosensitive ovarian cancer patients." (PMID 23251472, 2012). "CP, which is a potential oncogenic factor, is aberrantly expressed in various malignancies like lung cancer, ovarian cancer, and hepatic cancer, and can be involved in tumor growth and metastasis by regulating ferroptosis, angiogenesis, and tumor microenvironment (TME)." (PMID 37637428, 2023). "The expression of CYBRD1, LRP2, TFRC, SLC22A17, HEPH, SLC39A14, and PCBP2 involved in iron import was associated with poor OS of ovarian cancer, whereas the expression of LCN2, CP, SLC46A1, STEAP3, and LTF in this process was associated with improved OS in ovarian cancer." (PMID 38186569, 2023). "Therefore, we proposed a hypothesis asserting that the LINC00176/BCL3/CP axis may play a novel role in the progression and development of ovarian cancer via confirmation by a series of in vitro and in vivo experiments." (PMID 31668012, 2020). "In patients with confirmed ovarian cancer, VEGF, malondialdehyde, and ceruloplasmin had prognostic value, both in terms of progression-free survival and overall survival, especially in patients with the residual macroscopic disease." (PMID 36611458, 2023). "Conversely, 8 genes showed increased expression in ovarian cancer tissues, including LCN2, CP, TFR2, LRP2, MELTF, LTF, SLC11A2, and STEAP3." (PMID 38186569, 2023).
ovarian carcinoma (continued). "CP expression was higher in GBM, LGG, ovarian cancer (OV), kidney renal clear cell carcinoma (KIRC), and other tumor tissue samples compared to paraneoplastic tissues." (PMID 37637428, 2023). "The down-regulation of non-coding RNA ceruloplasmin (NRCP), identified as a highly expressed lncRNA in ovarian cancer, can lead to increased apoptosis, decreased cell proliferation, and inhibition of glycolysis." (PMID 36313430, 2022). "To test whether restoration of miR-497 expression in cisplatin-resistant ovarian cancer cells can enhance the response of cisplatin treatment in vivo, we established an orthotopic ovarian tumor model by implantation of A2780/CP-Tet-ON-miR-497 or A2780/CP-Tet-ON-miR-NS cells in nude mouse ovary." (PMID 26238185, 2015). "Ovarian cancer cells secrete high amounts of C3, whose non-canonical cleavage (independent of CP, AP and LP) leads to C3a production in the TME." (PMID 40370471, 2025). "In this study, three ferroptosis-related genes PRNP, ACSL1, and CP were picked out as the co-DEGs among different ovarian cancer datasets, with significantly decreased expression of PRNP and ACSL1 and increased expression of CP in ovarian cancer tissues when compared with normal ovarian tissues." (PMID 36213323, 2022).
viral infection (31 papers, 2015 to 2026). "It is believed that the CP and TF expression levels in the epithelial cells of genetically susceptible hosts may be significantly reduced when exposed to the joint action of virus infection and hormone factors." (PMID 37656227, 2023). "We demonstrated that HCPro2 interacts with both CI and CP in planta in forming PD-localized complexes during viral infection." (PMID 38437247, 2024). "Several studies have revealed the mechanism with which the UPS mediates the degradation of viral proteins to inhibit viral infection, such as through replicase, CP, MP, and γ b proteins." (PMID 36831257, 2023). "Transgenic potato plants expressing complementary RNA with the PLRV CP gene have shown similar resistance to viral infection as transgenic plants expressing the PLRV CP gene." (PMID 37176794, 2023). "It has been shown that overexpression of RSV CP in rice plants enhances resistance against virus infection." (PMID 38257773, 2023). "The application of viral CP genes in potato antiviral gene engineering is based on viral CP genes inhibiting virus uncoating so as to block virus infection." (PMID 37176794, 2023). "Highest point of viremia in viral infections typically occurs between 10 and 14 days, therefore, CP should be most effective if administered within the first week after the onset of symptoms." (PMID 36118915, 2022). "An analysis of the transcriptional activity of the PVX CP viral gene in plants showed that already on the 7th day after virus infection, RNA abundance was very high in the leaves of cv." (PMID 35204789, 2022). "For comparison, anti-RBD titers induced by viral infection with SARS-CoV-2 in convalescent individuals (CP), measured with the same ELISA platform for a different study are also plotted (grey circles)." (PMID 36152043, 2022). "As older studies about CP in previous viral infections had stated, CP was more effective if administered early in the course of the disease, before the peak viremia, where massive IgM and IgG antibodies were produced." (PMID 36118915, 2022). "About 4h after virus infection first became detectable, a neighboring cell in the direction of virus movement, showed the first faint traces of mCherry-CP." (PMID 29449856, 2018). "A transgenic is already developed for the okra shoot, and fruit borer; thus, it is required to develop more transgenics especially using CP genes for viral diseases like YVMV and ELCV." (PMID 28367155, 2017). "Viral infection at 48 h-pi altered transcription profiles in many of the GO subcategories within the BP, CP, and MF ontology." (PMID 28424677, 2017). "Because RdFV or RGDV infection activates HongrES1 expression, and thus the knockdown of RGDV P8 or RdFV CP expression accordingly decreases HongeES1 accumulation, which finally inhibits viral infection in male reproductive system and subsequent paternal virus transmission." (PMID 36894574, 2023). "The relative expression of the viral CP gene and accumulation of viral coat protein in systemically infected leaves increased gradually, and this result was consistent with the development of viral infection symptoms." (PMID 38140565, 2023). "The results obtained in the present work support the idea that the RNAs are competing for the CP, and it is therefore a limiting factor that could be used for interventions aimed at controlling virus infection." (PMID 28694514, 2017). "This suggests that RSV CP is an effector to induce AGO18 expression during viral infection." (PMID 25688565, 2015). "Importantly, CP-treated cells had ≥ 70 % cell viability within 24 hpi for all tested viruses compared to untreated cells which had significantly higher cell death following virus infection." (PMID 27484768, 2016). "Therefore, PA-mediated enhancement of RNA1 replication may be suitable for the production of CP subgenomic RNA during the late stage of viral infection." (PMID 26020241, 2015).
viral infection (continued). "The CP protein of turnip crinkle virus (TCV) can interact with TIP, a NAC transcription factor, in Arabidopsis to inhibit the salicylic acid pathway and promote virus infection." (PMID 37063211, 2023). "At 6 days post-inoculation (dpi), viral infection symptoms appeared on upper, uninoculated leaves of the PVX infected plants but not on the mock control plants, and the viral infection was verified by RT-PCR with PVX CP gene-specific primers." (PMID 31134032, 2019). "It is not clear what CP expression may specifically be doing to the cell, however, there are many lines of evidence linking viral infection and host chaperones." (PMID 40446071, 2025). "Viral infection, insert retention and GFP accumulation from LIYV-L2CGFP in upper leaves were confirmed by RT-PCR with primers amplifying the sequences of LIYV CP and the GFP expression cassette, and by immunoblot analysis using antibodies specific to LIYV CP and GFP." (PMID 29695039, 2018).
breast cancer (28 papers, 2011 to 2024). A primary or metastatic malignant neoplasm involving the breast. "Elevated serum CP levels have been linked to various cancers, including oral, thyroid, prostate, colon, and breast cancers, where they are associated with tumor invasion and metastasis." (PMID 39337685, 2024). "Increased expression of ceruloplasmin (CP) is associated with an unfavorable prognosis and immune infiltration in breast cancer." (PMID 38385087, 2024). "More importantly, improvement in obesity caused by energy restriction can significantly reduce the serum ceruloplasmin concentration in obese women, likely decreasing the risk of breast cancer in those subjects." (PMID 34413268, 2021). "In this study, we explored the water extract of CP, for its anticancer effects against breast cancer cells with different mutation types." (PMID 34122605, 2021). "Ceruloplasmin expression was only associated with the infiltration abundances of CD8+ T cells in normal-like breast cancer." (PMID 34413268, 2021). "In our study, alpha-2-macroglobulin and ceruloplasmin were both lower in pre-diagnostic breast cancer samples compared to the control samples." (PMID 21871081, 2011). "With 2D-nanoLC-MS/MS, afamin, apolipoprotein E and isoform 1 of inter-alpha trypsin inhibitor heavy chain H4 (ITIH4) were found to be higher in pre-diagnostic breast cancer (p < 0.05), while alpha-2-macroglobulin and ceruloplasmin were lower (p < 0.05)." (PMID 21871081, 2011). "Of the proteins detected with 2D-nanoLC-MS/MS, afamin, apolipoprotein E and an isoform of ITIH4 were slightly, but significantly higher and alpha-2-macroglobulin and ceruloplasmin slightly, but significantly lower in pre-diagnostic breast cancer samples compared to control samples." (PMID 21871081, 2011). "Interestingly, high serum levels of ceruloplasmin have been demonstrated in various cancers such as thyroid, prostate and colon cancer, and microarray analysis has linked this gene to tumor invasion and metastasis in breast cancer." (PMID 23251472, 2012). "In the mFMC group, there was marked protein expression of BCL6, TXNRD3, CP and BIRC6, which have been linked with poor prognosis in human breast cancer." (PMID 38951817, 2024). "It has been observed that altered CP levels follow chemotherapy or radiation in laryngeal, cervical, and breast cancers, with greater post-treatment decreases correlating with improved outcomes." (PMID 39337685, 2024). "The combination of PPD and cannabidiol (CBD-PPD coloading liposome, CP-liposomes) effectively inhibited the growth of the 4T1 breast cancer cell line more than that with CBD or PPD treatment alone." (PMID 39339339, 2024). "An MTT assay was performed to demonstrate the cytotoxic properties of Cur, Pacli, CP, Au-C, Au-P, and Au-CP in breast cancer cell lines (i.e., MDA MB 231, 4T1, and HEK 293)." (PMID 35216264, 2022). "The tumors significantly regressed in mice that received Cur, CP, Au-C, Au-CP, indicating the effectiveness of the treatments against breast cancers individually with Cur and Au-C and also in combination CP and Au-CP with the known anti-cancer drug Paclitaxel." (PMID 35216264, 2022). "Cytotoxicity was successfully induced by phytochemical combination of anticancer drugs at 10–20 μg/mL Cur, Pacli, and combinations of CP and Au-CP (5.0–10 μg/mL) concentrations in breast cancer cell lines." (PMID 35216264, 2022). "CP (ceruloplasmin) serves as a prognostic biomarker in many cancers, including bile duct cancer, bladder cancer, breast cancer, etc.." (PMID 35800363, 2022). "This demonstrated that the cytotoxicity of CP extract on the breast cancer cells lines is gene type dependent, and ER & PR phenotypes are correlated with the CP cytotoxicity." (PMID 34122605, 2021). "Consistent with the protein level, the mRNA level of ceruloplasmin was also lower in BRCA cells compared with normal breast cancer cells." (PMID 34413268, 2021).